LRRC27 (leucine rich repeat containing 27)
Synonyms: KIAA1674
Tractability: No criterion of Open Targets' tractability assessment is met for any kind of drug.
Gene: Protein-coding gene on chromosome 10 (132,332,154 to 132,381,508, forward strand). Ensembl gene ENSG00000148814.
Subcellular location (Human Protein Atlas): Golgi apparatus; Nucleoplasm
Genetic constraint (gnomAD): Loss-of-function variants: 53 observed, 50.13 expected, observed/expected ratio (o/e) 1.06, 90% interval 0.85 to 1.33. The upper end of that interval is the gene's LOEUF score, 1.33, which puts it in group 5 of 6, group 1 being the genes least tolerant of losing a copy. Missense variants: 691 observed, 647.66 expected, observed/expected ratio (o/e) 1.07, 90% interval 1 to 1.14. Synonymous variants: 270 observed, 254.13 expected, observed/expected ratio (o/e) 1.06, 90% interval 0.96 to 1.17.
Homologues: Orthologues: chimpanzee LRRC27 (96% identical), dog LRRC27 (59% identical), guinea pig LRRC27 (58% identical), pig LRRC27 (56% identical), mouse Lrrc27 (55% identical), rat Lrrc27 (53% identical), tropical clawed frog lrrc27 (28% identical). Paralogues in human: SCRIB (20% identical), LRRC1 (16% identical), LRRC7 (15% identical), LRRC8E (15% identical), PIDD1 (15% identical), PHLPP1 (15% identical), ERBIN (14% identical), LRCH3 (14% identical), LRCH4 (14% identical), LRRC8A (14% identical), MFHAS1 (14% identical), LRRC8D (14% identical), and 19 more.
Diseases named in the same sentence as LRRC27 in open-access papers:
LRRC27 is named in the same sentence as 8 diseases in open-access papers, as found by Europe PMC text mining. Sharing a sentence is not in itself a finding about the gene and the disease. The quoted sentences say what the papers report.
preeclampsia (2 papers, 2022 to 2023). Preeclampsia is a hypertensive disorder of pregnancy that is characterized by new-onset hypertension with proteinuria presenting after 20 weeks of gestation, and depending on mild or severe forms may initially present with severe headache, visual disturbances, and hyperreflexia. "LRRC27 is expressed in platelets and its overexpression is associated with preeclampsia, which, among other symptoms, manifests in high blood pressure." (PMID 36979743, 2023). "In this study, platelet leucine-rich repeat-containing protein 27 and 42 (LRRC27/42) subunits of volume-regulated anion channels (VRAC) were markedly overexpressed in preeclampsia." (PMID 35455936, 2022). "Our identification of increased expression of LRRC27/42 and S100A8/9 in platelets of preeclampsia is also novel." (PMID 35455936, 2022). "In addition, we showed that the facultative glucose transporter-3 (GLUT3) was overexpressed in PE; if LRRC27/42 functioned similarly as LRRC8A, both may operate in tandem with GLUT3 to enhance ‘resting state’ glucose entry in platelets and contribute to the prothrombotic tendency of preeclampsia." (PMID 35455936, 2022).
lung carcinoma (1 paper, 2024). "Moreover, five of the remaining genes showed significant results in at least one of the lung cancer types, including LRRC27 and PLEKHB1 in LUAD and ARNTL2, FOSL1, and PTBP3 in LUSC." (PMID 39410631, 2024).
mastitis (1 paper, 2024). Inflammation of breast tissue during lactation or postpartum due to an obstructed duct or infection. "The same region partially overlaps the CNVR_1549_P (the region comprising the JAKMIP3, DPYSL4, STK32C, LRRC27, PWWP2B) resulted associated with clinical mastitis in Mexican Holstein Cattle." (PMID 38771855, 2024).
type 2 diabetes (1 paper, 2020). "Although the roles of Serpina11, Cdh16, Lrrc27, and Lrrc66 in regulating islet function remain unclear, Acod1 is known to be important in modulating the immune system and mitochondrial function, and Fgf21 can protect against type 2 diabetes in mice by increasing insulin expression and secretion." (PMID 32527043, 2020).
LRRC27 also shares sentences with these, for which no sentence is quoted: COVID-19 (1 paper); glaucoma (1); high blood pressure (1); tumor (1).